SKP2 (S-phase kinase associated protein 2)
Diseases named in the same sentence as SKP2 in open-access papers (continued):
Sharing a sentence is not in itself a finding about the gene and the disease.
osteosarcoma (continued). "We reported that miR-506 reduced cell viability and motility and induced apoptosis by targeting Skp2 in osteosarcoma cells." (PMID 33621206, 2021). "Skp2 expression level in osteosarcoma cells after miR-506 mimics plus Skp2 plasmid cotransfection was determined by immunoblotting." (PMID 33621206, 2021). "Skp2 expression was reduced at a lower level in osteosarcoma cells treated with both Skp2 siRNA and miR-506 mimics compared with Skp2 siRNA transfection alone or miR-506 mimic transfection alone." (PMID 33621206, 2021). "The MTT data showed that upregulation of Skp2 promoted cell viability, while miR-506 mimics diminished viability of osteosarcoma cells." (PMID 33621206, 2021). "Upregulation of Skp2 has been reported in a broad spectrum of human cancers, including breast, prostate, pancreatic cancer, and osteosarcoma." (PMID 33621206, 2021). "Collectively, these results suggested that Skp2 has anti-apoptotic and pro-invasive activity in osteosarcoma cells." (PMID 30250282, 2018). "We showed that Skp2 is significantly overexpressed in osteosarcoma cell lines and that high levels of Skp2 are predictive of a worse metastasis-free and overall survival in patients." (PMID 30250282, 2018). "Similar to Skp2 knockdown, treatment with FKA also reduced Skp2 expression in osteosarcoma cell lines and blocked the invasion of osteosarcoma cells in vitro and lung metastasis in vivo." (PMID 30250282, 2018). "Skp2 mRNA levels were significantly elevated in several standard and patient-derived osteosarcoma cell lines compared to either normal human osteoblasts (NHOst-1) or human mesenchymal stem cell (MSC)-derived osteoblasts (NHOst-2) (p < 0.05)." (PMID 30250282, 2018). "As such, our study provides a framework for further investigation of the clinical utility of flavokawain A in preventing the progression of osteosarcoma as well as other Skp2-dependent cancers." (PMID 30250282, 2018). "During the course of our investigation, Ding and colleagues reported that overexpressing Skp2 leads to enhanced cellular growth, motility, and invasion in osteosarcoma, while increased apoptosis was observed in cell lines depleted of Skp242,43." (PMID 30250282, 2018). "Skp2 knockdown markedly reduced in vitro cellular invasion and in vivo lung metastasis in an orthotopic mouse model of osteosarcoma." (PMID 30250282, 2018). "In our study, a multi-pronged approach was undertaken to provide evidence that Skp2 is an important prognostic marker in osteosarcoma." (PMID 30250282, 2018). "To further evaluate the prognostic significance of Skp2 in osteosarcoma, we measured Skp2 expression by immunohistochemistry (IHC) using tissue microarrays (TMA) in which patient outcome data were available." (PMID 30250282, 2018). "To evaluate the impact of Skp2 knockdown on osteosarcoma growth and lung metastasis, we used an orthotopic mouse model in which tumor cells were injected into the proximal tibia of SCID mice." (PMID 30250282, 2018). "Together, these results establish the prognostic significance of Skp2 in osteosarcoma in a much more rigorous fashion than previously reported." (PMID 30250282, 2018). "Since the RhoA GTPase plays a crucial role in the invasiveness and metastasis of multiple cancers, it is likely that FKA or Skp2 knockdown blocks RhoA, leading to inhibition of invasiveness and lung metastasis in osteosarcoma." (PMID 30250282, 2018). "In summary, our study identified the F-box protein Skp2 as a potential therapeutic target for osteosarcoma." (PMID 30250282, 2018). "Our study revealed that high levels of Skp2 expression are predictive of a worse prognosis in osteosarcoma patients." (PMID 30250282, 2018). "Conversely, overexpression of Skp2 in osteosarcoma cell lines treated with the same FKA doses abrogated the effects of FKA on p21 and cleaved PARP." (PMID 30250282, 2018).
osteosarcoma (continued). "In this study, we provide evidence that Skp2 is a therapeutic target that plays an important role in the invasion and metastasis of osteosarcoma." (PMID 30250282, 2018). "In this study, we sought to identify the functional role and prognostic significance of Skp2 in osteosarcoma." (PMID 30250282, 2018). "In this report, we have identified the F-box protein Skp2 as a proto-oncogene that plays a role in osteosarcoma progression and metastasis." (PMID 30250282, 2018). "To determine the mechanisms underlying FKA-induced inhibition of Skp2, we next treated osteosarcoma cell lines 143B and SaOS-2 with increasing concentrations of FKA and examined its effects on Skp2." (PMID 30250282, 2018). "Together, our results suggest that FKA exerts its anti-metastatic effects in osteosarcoma by suppressing Skp2." (PMID 30250282, 2018). "Skp2 was found to be overexpressed in multiple osteosarcoma cell lines, including 5 standard and 8 primary patient-derived cell lines." (PMID 30250282, 2018). "Our findings revealed that Skp2 is a prognostic marker that is frequently overexpressed in osteosarcoma, and that genetic knockdown of Skp2 effectively inhibits osteosarcoma invasion and metastasis." (PMID 30250282, 2018). "Secondly, we aimed to explore the potential role for FKA as a Skp2-targeted agent in preventing osteosarcoma progression." (PMID 30250282, 2018). "First, we used multiple patient-derived and established cell lines to demonstrate that Skp2 mRNA and protein are overexpressed in osteosarcoma compared to normal osteoblasts." (PMID 30250282, 2018). "Taken together, we surmise that the anti-invasive and anti-metastatic effects of FKA in osteosarcoma cells are the result of FKA-induced depletion of Skp2." (PMID 30250282, 2018). "In osteosarcoma, our observation that RhoA is suppressed after depleting Skp2 is consistent with previous reports." (PMID 30250282, 2018). "SMO has been identified as a potential drug target in osteosarcoma, as its inhibitor cyclopamine promotes G1 arrests and represses expression of cyclin D1, cyclin E1, SKP2, and pRb." (PMID 23251412, 2012). "Finally, we report several mechanisms potentially used by osteosarcoma to escape from Skp2 targeting, including upregulation of Myc targets, induction of genomic instability, overexpression of alternative E3 ligases, and lineage plasticity." (PMID 41877584, 2026). "Additionally, our scRNA-seq analysis uncovered decreased expression of metastasis-related gene signatures in Skp2-disrupted osteosarcoma, which we validated by a strong reduction in lung metastasis in the Skp2 KO mice." (PMID 41877584, 2026). "Thus, targeting SETDB1 in osteosarcoma would represent a potential therapeutic strategy, as it would downregulate both SKP2 and TRAF4 (and their ability to activate AKT)." (PMID 38534381, 2024). "Skp2 has been known as an E3 ubiquitin ligase involved in osteosarcoma progression." (PMID 39324133, 2024). "Apoptosis was measured in osteosarcoma cells after Skp2 plasmid and miR-506 mimic transfections." (PMID 33621206, 2021). "This study demonstrated that suppression of Skp2 via upregulation of miR-506 might be a potential approach for osteosarcoma therapy." (PMID 33621206, 2021). "Moreover, miR-506 overexpression inhibited Skp2 expression in osteosarcoma cells, which was rescued by Skp2 overexpression." (PMID 33621206, 2021). "In addition, 15,16-dihydrotanshinone I inhibited proliferation and migration and induced apoptosis partly by targeting Skp2 in osteosarcoma cells." (PMID 33621206, 2021). "Moreover, upregulation of Skp2 accelerated cell viability and motility and rescued the tumor suppressive effect of miR-506 in osteosarcoma cells." (PMID 33621206, 2021). "Moreover, Transwell chamber invasion assay data showed that Skp2 plasmid transfection increased cell invasiveness and that miR-506 upregulation retarded cell invasion in osteosarcoma cells." (PMID 33621206, 2021).
osteosarcoma (continued). "To define whether miR-506 performed anti-motility effects via regulation of Skp2 in osteosarcoma cells, we measured the migratory activity of osteosarcoma cells after miR-506 mimic transfection in combination with Skp2 plasmid transfection." (PMID 33621206, 2021). "Our work presents the anticancer effect of miR-506 in osteosarcoma, and demonstrates that minimization of Skp2 by miR-506 might be a novel tactics for treating osteosarcoma." (PMID 33621206, 2021). "To ascertain whether miR-506 utilizes its antineoplastic activity via inhibition of Skp2 in osteosarcoma cells, we transfected Skp2 plasmid into cells and then added miR-506 mimics." (PMID 33621206, 2021). "In addition, high expression of Skp2 blocked miR-506-mediated suppression of invasion of osteosarcoma cells." (PMID 33621206, 2021). "Similarly, downregulation of Skp2 enhanced the antitumor activity induced by miR-506 overexpression in osteosarcoma cells." (PMID 33621206, 2021). "Stable knockdown of Skp2 abrogates EMT-induced methotrexate (MTX) resistance in osteosarcoma cells." (PMID 34068643, 2021). "Similarly, one group showed that suppression of Skp2 attenuated cell invasion and lung metastasis in osteosarcoma." (PMID 33621206, 2021). "To dissect whether miR-506 performs antitumor activity by targeting Skp2 in osteosarcoma cells, we transfected Skp2 siRNA and miR-506 mimics into MG63 and U2OS cells." (PMID 33621206, 2021). "In summary, miR-506 performs an anticancer activity via directly targeting Skp2 in osteosarcoma cells, indicating that inactivation of Skp2 by miR-506 might be an alternative strategy for treating osteosarcoma." (PMID 33621206, 2021). "Moreover, downregulation of Skp2 inhibited cell viability and decreased cell motility, which enhanced the antitumor activity induced by miR-506 mimic transfection in osteosarcoma cells." (PMID 33621206, 2021). "Moreover, we reported that Skp2 is involved in methotrexate-mediated resistance of osteosarcoma cells due to the induction of epithelial-mesenchymal transition." (PMID 33621206, 2021). "Although Skp2 has a critical role in osteosarcoma, the regulatory mechanism of Skp2 is unclear." (PMID 33621206, 2021). "Our previous studies showed that inhibition of Skp2 suppressed cell viability, stimulated apoptosis and led to cell cycle arrest, and attenuated cell migrative ability in osteosarcoma cells, whereas overexpression of Skp2 exerted the opposite effects on osteosarcoma cells." (PMID 33621206, 2021). "Moreover, Skp2 siRNA transfection led to increased apoptosis and promoted miR-506-induced apoptosis in osteosarcoma cells." (PMID 33621206, 2021). "Here, we reported that miR-506 targeted Skp2 and led to antitumor activity in osteosarcoma cells." (PMID 33621206, 2021). "In the current study, we present a new regulatory mechanism of Skp2 in osteosarcoma cells." (PMID 33621206, 2021). "The novel Skp2 inhibitor, compound 25, was shown to have antitumour activities and to cooperate with chemotherapeutic agents to suppress cancer cell survival, making it of potential interest in osteosarcoma." (PMID 32961800, 2020). "This study sought to elucidate the role of S phase kinase-associated protein (Skp2) in osteosarcoma invasion and metastasis and to explore flavokawain A (FKA), a natural chalcone from kava extract, as a potential Skp2 targeting agent for preventing osteosarcoma progression." (PMID 30250282, 2018). "Patients whose tumors expressed high Skp2 mRNA levels had a significantly worse metastasis-free survival compared to patients whose tumors expressed low Skp2 (p = 0.0095), suggesting that Skp2 may have pro-metastatic activity in osteosarcoma." (PMID 30250282, 2018). "Collectively, our results indicate that FKA may affect p27 levels via Skp2-independent mechanisms in osteosarcoma." (PMID 30250282, 2018).
osteosarcoma (continued). "Our data suggested that FKA may deplete Skp2 in osteosarcoma cells, through deneddylation and protein degradation, similar to what has been reported in prostate cancer." (PMID 30250282, 2018). "Taken together, these data suggest that FKA may reduce Skp2 expression in osteosarcoma through both transcriptional and post-translational mechanisms." (PMID 30250282, 2018). "Similarly, Skp2 overexpression in osteosarcoma cell lines was validated at the protein level using Western blot analysis." (PMID 30250282, 2018). "Interestingly, treating osteosarcoma cell lines with FKA also led to a decline in both Skp2 and p27 protein levels, along with decreased invasion and metastasis." (PMID 30250282, 2018). "Notably, both RhoA and MMP-9, which are positively regulated by Skp2 and play a role in osteosarcoma invasion, were suppressed following Skp2 knockdown." (PMID 30250282, 2018). "Furthermore, we found that depletion of Skp2 by short hairpin RNA (shRNA) or by FKA results in down-regulation of Skp2 and several of its targets, leading to inhibition of invasion and metastasis in osteosarcoma." (PMID 30250282, 2018). "Since patient survival data suggested that Skp2 may be a proto-oncogene in osteosarcoma, we next performed knockdown of Skp2 by shRNA to determine its biological effects on osteosarcoma cells." (PMID 30250282, 2018). "Together, our findings suggest that Skp2 is a promising therapeutic target in osteosarcoma, and that FKA may be an effective Skp2-targeted therapy to reduce osteosarcoma metastasis." (PMID 30250282, 2018). "Additionally, SKP2 knockdown has been found to significantly increase the expression of immunoinfiltration-related genes in osteosarcoma (OS) mouse models, suggesting that SKP2 may mediate immune rejection in the tumor microenvironment." (PMID 37679418, 2023). "Therefore, we determined whether miR-506 could directly target Skp2 in osteosarcoma to perform its tumor suppressive functions." (PMID 33621206, 2021). "Moreover, upregulation of Skp2 abrogated the antitumor function of miR-506 in osteosarcoma cells." (PMID 33621206, 2021). "Furthermore, downregulation of Skp2 moderated motility of osteosarcoma cells." (PMID 33621206, 2021). "It is also necessary to measure whether miR-506 has a negative association with Skp2 expression in osteosarcoma tissues." (PMID 33621206, 2021). "However, expression of p27, an Skp2 substrate, was not significantly affected by Skp2 knockdown, suggesting that in osteosarcoma, p27 levels may be regulated by Skp2-independent mechanisms." (PMID 30250282, 2018). "Accordingly, miR-506 mimics reduced Skp2 expression and subsequently promoted the expression of downstream targets, FOXO1 and p57, in osteosarcoma cells." (PMID 33621206, 2021). "However, the involvement of Skp2 in the pathobiology of osteosarcoma remains unclear." (PMID 30250282, 2018). "Similar to the effects of Skp2 knockdown, FKA also induced an accumulation of p21 and cleaved caspase-3 in osteosarcoma cell lines." (PMID 30250282, 2018). "Although p27 is a known substrate for Skp2-mediated ubiquitination in many cancers, our results demonstrated that levels of p27 were not significantly affected by Skp2 knockdown in osteosarcoma cell lines." (PMID 30250282, 2018). "In addition, our data showed that both genetic knockdown of Skp2 and pharmacologic suppression of Skp2 by FKA inhibits osteosarcoma invasion and lung metastasis." (PMID 30250282, 2018). "Although these authors did not analyze Skp2 in an in vivo model, their findings certainly corroborate our hypothesis that Skp2 plays an important oncogenic role in osteosarcoma pathobiology." (PMID 30250282, 2018).
ovarian carcinoma (19 papers, 2012 to 2026). A malignant neoplasm originating from the surface ovarian epithelium. "Our findings also indicated that combining MTF and SIM synergistically suppressed S-phase kinase-associated protein 2 (skp2) in ovarian cancer cells." (PMID 38489280, 2024). "It has been documented that Sal induces apoptosis in NCI/ADR-RES, DXR, and OVCAR-8 ovarian cancer cells via downregulation of S-phase kinase-associated protein-2 (Skp-2) and signal transducer and activator of transcription 3 (Stat3) inactivation." (PMID 29433536, 2018). "In fact, Skp2 expression by ovarian carcinomas is significantly associated with not only tumor stage but also lymph node metastasis." (PMID 23087899, 2012). "Similarly, the oncoprotein HBXIP promotes the migration of ovarian cancer cells through the upregulation of S-phase kinase-associated protein 2 by Sp1." (PMID 28388957, 2017). "Skp2, known to be upregulated in several types of cancers including ovarian cancer, possesses oncogenic activity due to its involvement in protein ubiquitination and degradation, subsequently regulating cellular metabolism, cell cycle and tumorigenesis." (PMID 38489280, 2024). "They revealed that the absence of Smurf1 represses cell proliferation, invasive capability, and EMT process in ovarian cancer through DAB2IP/AKT/Skp2 signaling loops." (PMID 35654587, 2022). "BRCA1, CDKN1B, PPP1CC, SKP2, and URI1 were clustered in subnetwork 8 and categorized as shared proteins in PCOS and ovarian cancer, hence suggesting an association between the two." (PMID 31216618, 2019). "S-phase kinase protein 2 (SKP2), an F-box protein, targets cell cycle regulators, and is frequently overexpressed in a variety of cancers, including ovarian cancer." (PMID 23371322, 2013). "SKP2 protein overexpression in epithelial ovarian cancers has been reported and this expression signature has been proposed as a prognostic factor." (PMID 23433318, 2013). "Our result showing the marked decrease of SKP2 protein after PI3K p110β-siRNA treatment confirmed that SKP2 is a downstream target of PI3K p110β isoform in ovarian cancer cells." (PMID 23371322, 2013). "Ectopic expression of miR-21 down-regulates the SKP2 in ovarian cancer cells." (PMID 38559562, 2024). "In ovarian cancer, the expression of miR-30a-5p is low, but overexpression of miR-30a-5p reduces migration, invasion, and metastasis by posttranscriptional down-regulating SKP2 gene expression." (PMID 38559562, 2024). "Importantly, they also reported that HBXIP was able to stimulate the activity of the Skp2 promoter via transcription factor Sp1 thus promoting the migration of ovarian cancer cells." (PMID 28388957, 2017). "We speculate that YAP can also promote ferroptosis via SKP2 in ovarian cancer." (PMID 36438923, 2022). "Similarly, the prognosis on ovarian cancers is influenced by Skp2." (PMID 23087899, 2012). "In subnetwork 8, long-term potentiation was identified as a significant pathway, where PPP1CC and PPP1CA directly interacted with three PCOS-ovarian cancer-shared PCOSrps—i.e., BRCA1, PPP1CC, and URI1—and indirectly interacted with two shared PCOSrps (CDKN1B and SKP2)." (PMID 31216618, 2019). "Analysis result indicated an obvious decreased p27 mRNA level in the paired ovary cancer epithelia cells, compared to that in the corresponding normal tissue cells, without p27 ligase Skp2 mRNA changing (GDS3592)." (PMID 30086790, 2018). "The expression of SKP2 (Z = -2.450, P = 0.014), cyclin E (Z = -2.068, P = 0.039), and stathmin (Z = -0.295, P = 0.768) was higher in primary low-grade ovarian carcinoma without metastasis than in borderline serous cystadenoma." (PMID 25106448, 2014). "In ovarian cancer cells, NC treatment led to the inhibition of migration and invasion through regulation of MMP-2/9 (Matrix metalloproteinase 2/9) and Skp2 (S-phase kinase-associated protein 2).27, 28 Altogether, without a doubt, NC exerts its anti-tumor activity in various types of human cancers." (PMID 30847386, 2019).